ODAPH (odontogenesis associated phosphoprotein)
Description:
May promote nucleation of hydroxyapatite.
Synonyms: C4orf26; FLJ23657; AI2A4
Tractability: Antibody: UniProt places it where antibodies can reach, with high confidence; UniProt predicts a signal peptide or a membrane-spanning region; its Gene Ontology location is reachable by antibodies, with medium confidence.
Gene: Protein-coding gene on chromosome 4 (75,556,048 to 75,565,871, forward strand). Ensembl gene ENSG00000174792.
Subcellular location: Secreted
Gene Ontology:
Molecular function: protein binding
Biological process: positive regulation of biomineral tissue development; positive regulation of enamel mineralization
Cellular component: extracellular region
Genetic constraint (gnomAD): Loss-of-function variants: 3 observed, 4.04 expected, observed/expected ratio (o/e) 0.74, 90% interval 0.33 to 1.7. That is too few expected variants to judge how well the gene tolerates losing a copy. Missense variants: 159 observed, 172.87 expected, observed/expected ratio (o/e) 0.92, 90% interval 0.81 to 1.05. Synonymous variants: 75 observed, 63.82 expected, observed/expected ratio (o/e) 1.18, 90% interval 0.97 to 1.42.
Homologues: Orthologues: pig ODAPH (75% identical), dog ODAPH (67% identical), rabbit ODAPH (63% identical), mouse Odaph (58% identical), rat Odaph (56% identical).
Diseases named in the same sentence as ODAPH in open-access papers:
ODAPH is named in the same sentence as 2 diseases in open-access papers, as found by Europe PMC text mining. Sharing a sentence is not in itself a finding about the gene and the disease. The quoted sentences say what the papers report.
amelogenesis imperfecta (2 papers, 2021 to 2023). Amelogenesis imperfecta (AI) represents a group of developmental conditions affecting the structure and clinical appearance of the enamel of all or nearly all the teeth in a more or less equal manner, and which may be associated with morphologic or biochemical changes elsewhere in the body. "Mutations of Odontogenesis-Associated Phosphoprotein (ODAPH, OMIM *614829) cause autosomal recessive amelogenesis imperfecta, however, the function of ODAPH during amelogenesis is unknown." (PMID 33441959, 2021). "It has also been identified as a functional motif in the protein odontogenesis-associated phosphoprotein (ODAPH), which functions in enamel mineralization and is mutated in various forms of amelogenesis imperfecta." (PMID 36979349, 2023).
cyst (1 paper, 2021). A sac-like closed membranous structure that may be empty or contain fluid or amorphous material. "Consistent formation of a cyst at the onset of maturation in OdaphC41*/C41* mice suggests that ODAPH plays a role in cell attachment directly, or indirectly by altering the expression of other genes necessary for attachment." (PMID 33441959, 2021).